PTP4A1 (protein tyrosine phosphatase 4A1)
Description:
Protein tyrosine phosphatase which stimulates progression from G1 into S phase during mitosis. May play a role in the development and maintenance of differentiating epithelial tissues. Enhances cell proliferation, cell motility and invasive activity, and promotes cancer metastasis.
Synonyms: PRL-1; PRL1; PTPCAAX1; HH72; PTP(CAAX1)
Tractability: Small molecule: a structure with a bound ligand is known; a high-quality ligand is known; it has a high-quality binding pocket; it belongs to a druggable protein family. Antibody: UniProt places it where antibodies can reach, with high confidence; its Gene Ontology location is reachable by antibodies, with medium confidence. PROTAC: ubiquitination databases record sites on it; its protein half-life has been measured; a small molecule that binds it is known.
Target class: Tyrosine protein phosphatase; Enzyme; Phosphatase; Protein Phosphatase
Gene: Protein-coding gene on chromosome 6 (63,521,746 to 63,583,588, forward strand). Ensembl gene ENSG00000112245.
Subcellular location: Cell membrane; Early endosome; Endoplasmic reticulum; Cytoplasm; Cytoplasm, cytoskeleton, spindle; Nucleus
Gene Ontology:
Molecular function: protein binding; protein tyrosine phosphatase activity
Biological process: positive regulation of cell migration
Cellular component: cytoplasm; cytoplasmic side of plasma membrane; early endosome; endoplasmic reticulum; plasma membrane; nucleus; spindle
Genetic constraint (gnomAD): Loss-of-function variants: 7 observed, 16.37 expected, observed/expected ratio (o/e) 0.43, 90% interval 0.24 to 0.8. The upper end of that interval is the gene's LOEUF score, 0.8, which puts it in group 3 of 6, group 1 being the genes least tolerant of losing a copy. Missense variants: 133 observed, 212.51 expected, observed/expected ratio (o/e) 0.63, 90% interval 0.54 to 0.72. Synonymous variants: 77 observed, 66.79 expected, observed/expected ratio (o/e) 1.15, 90% interval 0.96 to 1.39.
Homologues: Orthologues: chimpanzee PTP4A1 (100% identical), macaque PTP4A1 (100% identical), mouse Ptp4a1 (100% identical), rat Ptp4a1 (100% identical), pig PTP4A1 (99% identical), guinea pig PTP4A1 (98% identical), zebrafish ptp4a1 (92% identical), rat AABR07041247.1 (90% identical), rabbit PTP4A1 (83% identical), tropical clawed frog ptp4a1 (80% identical). Paralogues in human: PTP4A2 (86% identical), PTP4A3 (79% identical), CDC14A (35% identical), CDC14B (31% identical), CDC14C (29% identical), PTPDC1 (28% identical), CDKN3 (24% identical), PALD1 (14% identical).
Diseases named in the same sentence as PTP4A1 in open-access papers:
PTP4A1 is named in the same sentence as 52 diseases in open-access papers, as found by Europe PMC text mining. Sharing a sentence is not in itself a finding about the gene and the disease. The quoted sentences say what the papers report.
cervical carcinoma (10 papers, 2020 to 2025). A carcinoma arising from either the exocervical squamous epithelium or the endocervical glandular epithelium. "This lncRNA has been implicated in modulating the miR-299-3p/PTP4A1 axis in cervical cancer, while in colon cancer, it potentially interacts with miR-765." (PMID 40918504, 2025). "Both in vitro and in vivo studies demonstrate that USP30-AS1 enhances PTP4A1 expression by decoying miR-299-3p, thereby promoting the oncogenic potential of cervical cancer cells." (PMID 40918504, 2025). "CircNRIP1 promotes cervical cancer migration and invasion by sponging miR-629-3p and regulating the PTP4A1/ERK1/2 pathway." (PMID 35571014, 2022). "In conclusion, these results revealed that miR-629-3p significantly inhibited the migration and invasion of cervical cancer cells by targeting PTP4A1 via the ERK1/2 pathway." (PMID 32457332, 2020). "The USP30-AS1/miR-299-3p/PTP4A1 axis may serve as both a molecular marker for cervical cancer progression and a potential therapeutic target." (PMID 40918504, 2025). "For example, USP30-AS1 could regulate the miR-299-3p/PTP4A1 axis resulting in enhancement of cervical cancer progression." (PMID 35260141, 2022). "In addition, USP30-AS1 increases the oncogenicity of cervical cancer cells by upregulating PTP4A1 through the USP30-AS1/miR-299-3p/PTP4A1 network." (PMID 35528236, 2022). "In addition, circNRIP1 was revealed to promote development in cervical cancer via the miR-629-3p/PTP4A1 axis." (PMID 34811346, 2021). "Since these findings suggested that circNRIP1 may function in cervical cancer cells by sponging miR-629-3p, we examined whether circNRIP1 regulates the expression of PTP4A1, the target gene of miR-629-3p." (PMID 32457332, 2020). "Considered together, these findings support the hypothesis that circNRIP1 promotes cervical cancer cell migration and invasion, at least partially, by sponging miR-629-3p and regulating the PTP4A1/ERK1/2 pathway." (PMID 32457332, 2020). "Finally, the study indicated that circNRIP1 promotes migration and invasion in cervical cancer by sponging miR-629-3p and regulating the PTP4A1/ERK1/2 pathway." (PMID 32457332, 2020). "Protein tyrosine phosphatase 4A1 (PTP4A1), another potential marker in MEC, is found overexpressed in cervical cancer, prostate cancer, pancreatic cancer, colorectal cancer, gastric cancer, liver cancer, and esophageal cancer." (PMID 36527158, 2022).
breast carcinoma (9 papers, 2016 to 2022). "BNIP3 silencing may be mediated by the lncRNA RP11-317-J19.1, allowing the protein encoded by PTP4A1 to function normally, which may induce the uncontrolled proliferation and migration of breast cancer cells." (PMID 34226298, 2021). "Inhibition of PTP4A1 gene in MDA-MB-231 breast cancer cell lines by an increase in miR-944 expression impairs cell invasion." (PMID 34249670, 2021). "PTP4A1 expression is regulated by microRNAs that control cellular processes in breast cancer, whereas miR-601 targets PTP4A1 to inhibit breast cancer growth and invasion." (PMID 34226298, 2021). "Another study also illustrated that miR-601 suppressed the cell growth and invasion in breast cancer via targeting PTP4A1." (PMID 31547835, 2019). "We tested two predicted OCN pairs in each cancer type, including NCSTN and DNM1, and NCSTN and OGT in liver cancer; CCNA2 and PTP4A1, and HIF1A and PARP1 in lung cancer; and CCNA2 and PTP4A1, and PLK1 and PTP4A1 in breast cancer." (PMID 31097707, 2019). "For example, as we and others have shown previously, pharmacological inhibition of the adenosine receptor ADORA2B strongly inhibits breast cancer in mice, as do monoclonal antibodies directed against PTP4A1 (PRL1)." (PMID 28411283, 2017). "Our results pointed out that miR-944 is a novel upstream negative regulator of SIAH1 and PTP4A1 genes and provided for the first time evidence for its functional role in migration and invasion of breast cancer cells." (PMID 27377268, 2016). "PTP4A1 play key role in cancer cell growth and invasion of breast cancer cells, but this gene might be responsible for improvement of pituitary prolactinoma." (PMID 33709028, 2021). "In addition, our data pointed out that knockdown of gene expression by miR-944 could represent a molecular tool to specifically inhibit relevant druggable targets such as SIAH1 and PTP4A1 in breast cancer." (PMID 27377268, 2016). "Our data provided evidences about the role of miR-944 as a novel upstream negative regulator of PTP4A1 and SIAH1 and contributed for the understanding of the molecular mechanisms controlling cell migration and invasion in breast cancer." (PMID 27377268, 2016).
lung carcinoma (7 papers, 2016 to 2025). "We found that, indeed, PTP4A1 levels correlate with loss of fitness score upon PTP4A1 knockout in lung cancer CLs in Broad Institute’s CCLE53 and CRISPR Project Score51 datasets." (PMID 39995872, 2025). "Intriguingly, our targeted investigation indicates that tipifarnib treatment or silencing of the farnesylation substrate PTP4A1 in STK11-mutant lung cancer cells results in inhibition of proliferation as well as impaired tonic interferon signaling." (PMID 39995872, 2025). "Meanwhile, the invasion-promoting effect of PTP4A1 was also revealed in colorectal cancer, lung cancer and HCC." (PMID 27655691, 2016). "PTP4A1 is overexpressed in STK11-mutant NSCLC, but the functional impact of PTP4A1 in lung cancer is so far unknown." (PMID 39995872, 2025). "Rho family GTPases were responsible for increased cell motility in PTP4A1 overexpressed colorectal cancer and c-Src expression played an important role in PTP4A1 regulated lung cancer, whereas PTP4A1-mediated E-cadherin expression through PI3K/AKT signaling pathway was crucial to HCC motility." (PMID 27655691, 2016). "The titer of autoantibodies against MFGE8, NRAS, PTP4A1, RRAS2 was measured in serum of 80 esophagus cancer cases (ECs), 80 hepatocellular carcinoma cases (HCCs), 80 lung cancer cases (LCs), and 80 healthy controls by ELISA." (PMID 33718231, 2021).
esophageal cancer (4 papers, 2014 to 2023). A primary or metastatic malignant neoplasm involving the esophagus. "In the present study, in the nine samples used for qPCR analysis, the regulational role of PTP4A1 was found to be highly associated with p27, suggesting that PTP4A1 upregulation may be associated with the prognosis of esophageal cancer." (PMID 24604236, 2014). "In conclusion, the combination of H-CTCs and PTP4A1 expression can help predict the efficacy of neoadjuvant therapy in patients with esophageal cancer more sensitively and specifically." (PMID 38134119, 2023). "Advanced TNM stage and lymph node metastasis are influencing factors for increased CTCs and poor expression of PTP4A1 in patients with esophageal cancer." (PMID 38134119, 2023). "Third, multiple prediction models will be established based on the expression of PTP4A1 in CTCs to predict lymph node metastasis and efficacy of neoadjuvant therapy in patients with esophageal cancer." (PMID 38134119, 2023). "Advanced tumor-node metastasis (TNM) stage (odds ratio = 12.063) and lymph node metastasis (odds ratio = 13.541) were influencing factors of PTP4A1+MCTC expression disorders in patients with esophageal cancer." (PMID 38134119, 2023). "PTP4A1 expression in the CTCs of patients were analyzed by regression analysis, and its correlation with the clinical characteristics of esophageal cancer was discussed." (PMID 38134119, 2023). "Correlation of CTC subtypes and PTP4A1 expression with the efficacy of neoadjuvant therapy in esophageal cancer." (PMID 38134119, 2023). "In conclusion, advanced TNM stage and lymph node metastasis are factors influencing the increase in CTCs and the blockage of PTP4A1 expression in patients with esophageal cancer." (PMID 38134119, 2023). "It is suggested that advanced stages of TNM and lymph node metastasis will increase the peripheral blood CTC count and hinder the expression of PTP4A1, thereby affecting the prognosis of patients with esophageal cancer." (PMID 38134119, 2023). "CTCs combined with PTP4A1 expression can help better predict treatment efficacy in patients with esophageal cancer, which has important clinical value in blocking the disease progression and achieving individualized treatment of esophageal cancer metastasis." (PMID 38134119, 2023). "The objective of this study is to investigate the expression of protein tyrosine phosphatase type I (PTP4A1) in circulating tumor cells (CTCs) in patients with early- and intermediate-stage esophageal cancer and its clinical value in evaluating patient prognosis." (PMID 38134119, 2023). "In addition, this study found that PTP4A1 in combination with CTCs was highly predictive of the efficacy of adjuvant therapy in patients with esophageal cancer." (PMID 38134119, 2023). "Accordingly, this study explored the factors related to recurrence and metastasis in patients with esophageal cancer and established a predictive model using different CTC subtypes and PTP4A1 expression to evaluate the predictive efficacy of PTP4A1 for the treatment of esophageal cancer." (PMID 38134119, 2023).
hepatocellular carcinoma (4 papers, 2021 to 2025). A malignant tumor that arises from hepatocytes. "Adenoviral overexpression of PTP4A1 in human hepatoma cells increased the mRNA levels of FGF21 compared to controls, and shRNA-mediated PTP4A1 knock-down in human hepatoma cells reduced the mRNA levels of FGF21 compared to controls." (PMID 36793871, 2023). "Consistent with mouse data, human hepatoma cells treated with bovine serum albumin-oleic acid (BSA-OA) tended to increase PTP4A1 mRNA levels compared to controls." (PMID 36793871, 2023). "Supporting our findings, PTP4A1 has previously been shown to protect RIG-I from SHP2/PTPN11-dependent degradation, and knock-out of PTP4A1 reduced RIG-I levels and abolished RIG-I-dependent upregulation of IFNB1 in HepG2 hepatocellular carcinoma cells." (PMID 39995872, 2025). "PTP4A1 was found to be overexpressed in OSCC tissue and cell lines consistent with previous studies in ovarian carcinoma, intrahepatic cholangiocarcinoma, and hepatocellular carcinoma." (PMID 37773151, 2023).
intrahepatic cholangiocarcinoma (3 papers, 2016 to 2023). A carcinoma that arises from the intrahepatic bile duct epithelium in any site of the intrahepatic biliary tree. "PTP4A1 activates PI3K/AKT signaling and is pro-oncogenic in intrahepatic cholangiocarcinoma and is a critical enhancer of oncogenic TGFβ mediated signaling." (PMID 37773151, 2023). "However, the clinical implications and biological function of PTP4A1 in intrahepatic cholangiocarcinoma (ICC) remains unknown." (PMID 27655691, 2016).
brain glioma (2 papers, 2022). A malignant glioma that involves the brain. "MiR-339-5P inhibits angiogenic mimicry, migration, and invasion of brain glioma U251 cells by inhibiting the PTP4A1/HMGB1 signal pathway." (PMID 35872698, 2022). "MiR-339-5p is a tumor suppressor, inhibiting PTP4A1/HMGB1 signal pathway it suppresses vasculogenic mimicry, migration, and invasion of brain glioma U251 cells." (PMID 36354672, 2022).
gastric cancer (2 papers, 2021 to 2022). A primary or metastatic malignant neoplasm involving the stomach. "In addition, we selected the serum of 80 ECs, 80 HCCs, and 80 LCs and measured the titer of four TAAbs (anti-MFGE8, anti-NRAS, anti-PTP4A1, anti-RRAS2) by ELISA to verify the specificity of four TAAbs in gastric cancer." (PMID 33718231, 2021).
glioma (2 papers, 2022 to 2025). A benign or malignant brain and spinal cord tumor that arises from glial cells (astrocytes, oligodendrocytes, ependymal cells). "PTP4A1 is overexpressed in human glioma, and inhibition of PTP4A1 through microRNA (miRNA) 339-5p abrogates angiogenic mimicry, migration and invasion in a glioma cell line." (PMID 42135822, 2025). "Based on this, the present research investigated the expressing level of miR-339-5p in glioma and its molecular mechanism in glioma and its role in the PTP4A1/HMGB1 pathway, providing a valuable reference for the diagnoses and therapies of glioma." (PMID 35872698, 2022). "The findings demonstrated that miR-339-5p reduced the luciferase activity of PTP4A1-WT and that PTP4A1 expression was increased in glioma samples." (PMID 35872698, 2022). "Finding miR-339-5p inhibitory functions in glioma through PTP4A1/HMGB1 pathway." (PMID 35872698, 2022).
lung fibrosis (2 papers, 2017 to 2021). "Since lung fibrosis is a frequent and potential life threatening complication of SSc, we sought to determine whether promotion of TGFβ signaling is a conserved function of PTP4A1 between dermal and lung fibroblasts." (PMID 29057934, 2017).
mucoepidermoid carcinoma (2 papers, 2022 to 2025). A carcinoma morphologically characterized the presence of cuboidal mucous cells, goblet-like mucous cells, squamoid cells, cystic changes, and a fibrotic stromal formation. "Finally, the exclusive biomarkers for the 6 most common types of SGTs were uncovered by comparative analysis, and PTP4A1 was demonstrated as a useful diagnostic biomarker for mucoepidermoid carcinoma." (PMID 36527158, 2022). "For instance, through the establishment of a biobank comprising 45 salivary gland tumor organoids, researchers successfully identified subtype-specific biomarkers such as protein tyrosine phosphatase 4A1 (PTP4A1), offering new diagnostic criteria for mucoepidermoid carcinoma." (PMID 41425705, 2025).
oral squamous cell carcinoma (2 papers, 2023 to 2025). "Here, we report a novel role for PTP4A1 in oral squamous cell carcinoma (OSCC) growth and development." (PMID 37773151, 2023).
ovarian carcinoma (2 papers, 2016 to 2023). A malignant neoplasm originating from the surface ovarian epithelium. "Results from previous studies of PTP4A1 in ovarian carcinoma and HCC regarding its clinical implications were consistent with our findings." (PMID 27655691, 2016).
systemic sclerosis (2 papers, 2017 to 2021). A chronic disorder, possibly autoimmune, marked by excessive production of collagen which results in hardening and thickening of body tissues. "Here, the authors show that PTP4A1 is highly expressed by fibroblasts from patients with systemic sclerosis and promotes TGFβ activity via SRC–ERK–SMAD3 signaling." (PMID 29057934, 2017).
age (1 paper, 2024). A temporal measurement of the time period elapsed since an identifiable point in the life cycle of an organism. "The interplay between NFκB, PDGF-BB, LY6E, ID3, PTP4A1, and FOS in age-related vascular endothelial dysfunction and related pathologies underscores the complexity of molecular mechanisms governing vascular health." (PMID 38674087, 2024).
alcohol dependence (1 paper, 2011). Physical and psychological dependence on alcohol. "Expression of PHF3 and PTP4A1 transcripts was significantly correlated with expression of many alcoholism-related genes in brain, including those in the dopaminergic, serotoninergic, GABAergic, glutamatergic, histaminergic and endocannabinoid systems." (PMID 22096494, 2011). "This might suggest that the majority of the functions of PHF3-PTP4A1 contributed to the risk for alcohol dependence, and that the regulatory pathway via which these SNPs caused alcohol dependence might be related to the PHF3 and PTP4A1 proteins per se." (PMID 22096494, 2011). "We conclude that the PHF3-PTP4A1 region appears to harbor a causal locus for alcohol dependence, and proteins encoded by PHF3 and/or PTP4A1 might play a functional role in the disorder." (PMID 22096494, 2011). "PHF3 and PTP4A1 might also influence alcohol dependence by interacting with other genes." (PMID 22096494, 2011). "Third, many PHF3-PTP4A1 SNPs had significant (in PHF3) or slight (in PTP4A1) potential for altering the secondary RNA structure (predicted by MFOLD), providing additional evidence in support of the hypothesis that PHF3-PTPA41 per se contributed to alcohol dependence." (PMID 22096494, 2011).
anaemia (1 paper, 2009). "The lack of evidence for a response by Ptp4a1 and Tnfrs11a to infection is consistent with previous reports of a blunted response to erythropoietin in the anaemia of chronic disease." (PMID 19365556, 2009).
colon tumors (1 paper, 2013). "Interestingly, the gene expression levels of Ptp4a1 and Ptp4a2 were both downregulated 64% and 36% (p<0.0001 and p<0.05), respectively, in colon tumors relative to normal tissue." (PMID 23555575, 2013).
coronary artery disease (1 paper, 2024). "The association between PTP4A1 and the pathogenesis of coronary artery disease was observed to be substantial." (PMID 38674087, 2024). "FOS, conversely, contributes to the growth and longevity of cardiomyocytes and intersects with eNOS signaling, while PTP4A1 has a notable role in the development of coronary artery disease." (PMID 38674087, 2024). "PTP4A1, a tyrosine phosphatase, is significant in endothelial cell dynamics and coronary artery disease." (PMID 38674087, 2024). "The involvement of PTP4A1 in endothelial cell migration and coronary artery disease, alongside FOS’s contribution to endothelial cell functions, underscores the significance of these genes in maintaining vascular integrity and function." (PMID 38674087, 2024).